APC (APC regulator of Wnt signaling pathway)
Diseases named in the same sentence as APC in open-access papers (continued):
Sharing a sentence is not in itself a finding about the gene and the disease.
colon carcinoma (continued). "However, β-catenin accumulation in the nucleus and cytoplasm is frequently observed in colon cancer cases with APC mutations." (PMID 28947978, 2017). "Do mutations in the gene for APC lead to colon cancer because they alter the cell’s metabolism?" (PMID 28397687, 2017). "In colon cancer and invasive endocrine tumor cells induced by APC mutation, CIN is very distinct." (PMID 27065015, 2016). "In the present study, APC mutations were identified in 45% of colon cancers, while the frequency of APC mutations in MSS CRC samples published by The Cancer Genome Atlas (n = 195) would have been 51% when restricted to regions of the gene that are covered by the TSACP." (PMID 27729614, 2016). "The majority of sporadic and FAP colonic tumors involve mutations that inactivate the APC gene." (PMID 26959117, 2016). "The APC gene is a tumor suppressor gene associated with the development of sporadic colon cancer." (PMID 27649156, 2016). "The current study showed that mutations in the APC tumor suppressor gene that could be detected by TSACP analysis are associated with poor survival of 5-FU-treated stage III MSS colon cancer patients." (PMID 27729614, 2016). "Mutation of the WNT-pathway component APC was observed in 17 of the 19 colon cancer patients." (PMID 27245685, 2016). "In addition, LXR expression was found to be downregulated in colon tumors of APC-deficient mice compared with adjacent normal mucosa." (PMID 27092172, 2016). "We provide evidence to demonstrate that DDX3 may promote tumor invasion in APC-mutated colon cancer cells via the β-catenin/ZEB axis." (PMID 27007150, 2016). "Mutational inactivation of APC leads to the accumulation and nuclear translocation of β-catenin, resulting in aberrant activation of the canonical Wnt signaling pathway implicated in colon cancer development." (PMID 26311738, 2015). "However, in the presence of mutation in APC gene, PPARγ has been reported to be elevated in the later stages and promote the progression of colon cancer." (PMID 24999478, 2014). "Inactivation of both alleles of the APC gene is common in colon cancers." (PMID 24790607, 2014). "Breast cancer lacks classical Wnt activating mutations (such as APC) that are seen in colon cancer." (PMID 25174825, 2014). "Common APC loss in colon cancer, such as in HT29, might suggest total independence from WNT ligands for pathway activation and thus the inability of blockade of upstream ligand events to affect metastases." (PMID 24920608, 2014). "The APC gene was the only gene reportedly associated with colon cancer." (PMID 23301059, 2013). "Furthermore, a mouse model of colon cancer driven by loss of APC shows that colon tumour formation depends on continuous c-Myc expression." (PMID 24098375, 2013). "Importantly, the β-catenin accumulation induced by either Wnt ligand stimulation or mutation of APC/β-catenin in colon cancer cells is dependent on SRSF1 and SRSF9." (PMID 23592547, 2013). "Notably, it was able to promote β-catenin degradation in SNU475 hepatoma cells, which carry an axin mutation, as well as in SW480 colon cancer cells with APC mutation, and suppressed the growth of CRT-positive cancer cells." (PMID 23071615, 2012). "The results could have implications for preventing or retarding the onset of colon cancer in people with inherited or acquired mutation of one APC allele." (PMID 21857949, 2011). "Mutation of APC causes Familial Adenomatous Polyposis, an inherited form of colon cancer." (PMID 21311754, 2011). "This explains why most colon cancers are initiated by APC mutation." (PMID 21857949, 2011). "The fact that mutations in APC strongly predispose to colon cancer is well established." (PMID 21859464, 2011). "Similarly, GSEA of hsa-miR-519a-transfected STF-3a cells showed significant enrichment of the geneset LIN_WNT_UP, comprising Wnt target genes identified by expression of the Wnt antagonist APC in APC-deficient SW480 colon cancer cells." (PMID 22194702, 2011).
colon carcinoma (continued). "Mutation in the Adenomatous polyposis coli (APC) or β-catenin genes, are associated with majority of human and rat colon tumors and were proved to repress the degradation of the protein and generate β-catenin accumulations, which leads to activation of the oncogenic β-catenin-Tcf pathway." (PMID 20346115, 2010). "A truncated APC protein similar to those associated with colon cancers was unable to activate ASEF." (PMID 19845967, 2009). "A case in point is the association of mutations of APC with most of human colon tumors." (PMID 19586554, 2009). "However, two paperspublished ten years ago reported that troglitazone and rosiglitazone increased occurrenceof colon tumors in mice-caring mutations in the APC gene." (PMID 18779870, 2008). "However, although PPARγ acts as a tumor suppressor in colon cancer, colon tumors with mutations in the APC gene appear to be exceptions, sincethiazolidinediones promote growth in these tumors." (PMID 17389773, 2007). "In the Min mouse model of APC deficiency, ligands for PPARγ can increase colon tumour growth." (PMID 15583697, 2005). "Therefore, future studies will determine whether STRAP is a molecular target for the treatment of colon cancer in patients with APC mutation or Wnt/β-Catenin activation." (PMID 40558481, 2025). "Indeed, APC somatic truncation mutations are observed in more than 90% of human colon cancers." (PMID 39200196, 2024). "Thus, we conclude that eIF3a plays an important role in intestinal/colon tumorigenesis and inhibiting eIF3a may intercept APC mutation-induced colon tumor production." (PMID 39413959, 2024). "Together, we conclude that eIF3a upregulation in colon cancer is due to APC mutation and it participates in colon tumorigenesis by adding a translational control axis in the Wnt/β-catenin signaling pathway and that it can serve as a potential target for colon cancer intervention." (PMID 39413959, 2024). "Thus, it is likely that APC mutation causes eIF3a upregulation in human colon cancer." (PMID 39413959, 2024). "However, early APC mutations are acquired in over 80% of colon cancer patients, leading to the cytosolic accumulation of β-catenin, an intracellular signal transducer in transcriptional regulation that, in combination with TCF/Lef1, promotes proliferation and inhibits apoptosis." (PMID 37259421, 2023). "We propose that this is through the direct modulation of GSK-3 activity and that disrupted splicing associated with APC loss of function mutations may contribute to craniofacial defects during zebrafish development as well as the pathogenesis of colon cancer in humans." (PMID 37489330, 2023). "Activation of mTORC1 by APC truncations is clearly evident in zebrafish embryos with the homozygous apcmcr/mcr mutation, in adenomas from mice with the Apcmin mutation, in sporadic colonic adenomas and colon cancer in humans, and in adenomas from patients with FAP." (PMID 37759479, 2023). "Importantly, mutations in APC contribute to 5-FU resistance in colon cancer cells." (PMID 34203665, 2021). "Indeed, most colon cancer cells are heterozygous for APC mutations." (PMID 33430034, 2021). "Therefore, mutational inactivation of APC abrogates the β-catenin destruction complex and results in aberrant activation of Wnt/β-catenin signaling, which is considered as the primary step in colon cancer development." (PMID 33597597, 2021). "Interestingly, while in colon cancers the APC gene is recurrently affected by somatic mutations, it has been found that APC promoter hypermethylation is a frequent event in GC patients, even though somatic mutations were also found in a small percentage of patients." (PMID 32752096, 2020). "JAK/STAT3 signal transduction has the ability to suppress tumor immunity, and the application of JAK inhibitors in colon cancer can suppress sporadic colon cancer caused by mutations in APC inhibitory genes, and it may also provide treatment opportunities for other oncogenes with resistance." (PMID 33117713, 2020).
colon carcinoma (continued). "Hence, it would be extremely interesting to analyze whether Plk1 can also control APC localization in human cells, particularly considering that most sporadic colon cancers are attributable to APC mutations." (PMID 33135999, 2020). "Whether it be germline deletions resulting in familial adenomatous polyposis, or sporadic mutations identified in colon cancer patients, an overwhelming number of these pathological mutations result in APC truncations, which remove the β-catenin and Axin 1 and 2 (SAMP) binding sites." (PMID 32823838, 2020). "It has been previously reported that APC mutations may initiate the process of colon cancer development as one of the earliest genomic aberrations, but we did not obtain clear results for the early occurrence of APC mutations in the gene-level experiments shown in the previous section." (PMID 29697365, 2018). "However, DCLK1+ cells are able to generate colon cancers when APC loss was followed by an inflammatory stimulus such as colitis: the effect of the inflammatory stimulus was active in inducing tumorigenesis when both were given immediately after APC loss or after three months." (PMID 29652830, 2018). "Since lung cancer cells generally lack APC and β-catenin mutations that are frequently found in colon tumors, they probably have to rely on multiple changes in the Wnt pathway regulators, which may complement each other in sustaining high levels of Wnt signaling." (PMID 25909283, 2015). "Thus, APC-mutation-induced changes in a counter-current-like mechanism will increase the number of proliferative cells (SCs, rapidly proliferating cells), contributing to colon cancer initiation and adenoma development." (PMID 24224156, 2013). "However, it is already known that a minor pathway to colon cancer exists involving point mutations in the beta-catenin gene so our calculations for initiation rates are in fact a weighted average of the APC, beta-catenin, and other unknown minor pathways." (PMID 24195059, 2013). "Moreover, mutations in APC are found in around 80% of sporadic colonic tumors." (PMID 21859464, 2011). "Additionally, the FasL TCF/LEF-1 binding element could serve as an enhancer in colon cancer cells carrying APC mutations." (PMID 22022540, 2011). "However, recent findings revealed that Wnt ligands or inhibitors could affect the growth and survival of colon cancer cells in spite of the presence of APC or CTNNB1 mutations." (PMID 19773752, 2009). "That APC might be involved in the exchange between Groucho and β-catenin in vivo has importance for Wnt signaling and colon cancer where APC is either mutated or lost in these tumors, and it underscores how fundamental the unknowns are for Groucho interaction with the Wnt signaling pathway." (PMID 19460168, 2009). "Furthermore, mutations in APC are found in the majority of sporadic cases of colon cancer." (PMID 12610503, 2003). "Strap knockout sensitizes colon tumors to chemotherapy, delays APC-induced tumor progression, and reduces cancer cell stemness." (PMID 40558481, 2025). "Sohlh2 suppressed the proliferation, migration, and invasion of ovarian, breast and colon cancer cells through transcriptional regulation of P21, Cyclin D1 and APC." (PMID 40418209, 2025). "APC (APC Regulator of WNT Signalling Pathway) is another frequently analysed methylation biomarker specific to colon cancer that is often hypermethylated in BC specimens with high specificity (94.2%–100%) and various ranges of sensitivity (17%–93.45%)." (PMID 40524349, 2025).
colon carcinoma (continued). "Having determined the APC gene as a major mutational driver in FAP patients, resulting in 100% risk of developing colon cancer if left untreated, allowed us to identify patients at the highest risk of cancer." (PMID 39944699, 2025). "Akt is a key player in the growth of colon tumors; it stops GSK3β/APC/axin from breaking down β-catenin and increases the expression of oncogenes like c-Myc and cyclin D1 that target β-catenin." (PMID 39811247, 2025). "In our study, the APC gene was less expressed in the colon tumor compared to the adjacent colonic mucosa and to the mucosa of healthy controls." (PMID 39200196, 2024). "Gene enrichment analysis demonstrated that the high expression of TRPM8 is associated with the excessive activation of the Wnt-Frizzled signal and the downregulation of Adenomatous polyposis coli (APC) in colon cancer patients." (PMID 39633507, 2024). "AS isoforms of APC, such as cAPC and BS-APC, have demonstrated significant efficacy in inhibiting the growth of colon tumor cells." (PMID 39004679, 2024). "BRAF mutation is predominant in proximal colon cancers in the context of CIMP-H and with a tendency to be mutually exclusive of APC mutations." (PMID 38360902, 2024). "This intriguing correlation between APC mutations, aberrant localization of β-catenin, and an enhanced EMT status suggests a complex interplay between these factors in colon cancer progression." (PMID 38414697, 2024). "For example, overexpression of miR-494 inhibits the expression of APC, an inhibitor of the β-catenin signaling pathway, promoting cell proliferation and tumorigenesis in colon cancer." (PMID 39133165, 2024). "On the other hand, in colon cancer cells expressing a truncated form of APC (APC-ΔC), PLK1 appears to have a tumor-suppressive function." (PMID 39273409, 2024). "This is important, considering that APC mutations have been shown to cooperate with BRAF and KRAS mutations for the development of colon cancer, which are also genetic alterations present in HT-29 and SW480 cells, respectively." (PMID 37259421, 2023). "Whilst information is lacking on the mutational status of all xenograft models, the authors stated that the colon cancer model was wildtype for both APC and CTNNB1." (PMID 37048063, 2023). "Comparison between APC-MUT and APC-WT colon cancers suggested a nonspecific relationship between RAI14 expression and APC states, However, RAI14 exhibited more notable differences between the two subtypes in APC-MUT colon cancers than in APC-WT colon cancers." (PMID 36934880, 2023). "The same study also identified a mutually exclusive relationship between mutations in RNF43 and APC in CRC patients, suggesting an activating role of truncating mutations in RNF43 in the WNT pathway of colon tumours." (PMID 37048063, 2023). "In a few instances, including expression of claudin 7 in CMS3 colon cancers and expression of occludin in CMS1 and CMS3 colon cancers, upregulation was observed in APC-mutated cases, implying a central role of the WNT/β-catenin cascade in these cases." (PMID 37998722, 2023).
colon carcinoma (continued). "The heterogeneity and the significance of prognostic biomarkers in APC-mutant tumors were further validated in the Clinical Proteomic Tumor Analysis Consortium (CPTAC) colon cancer cohort." (PMID 36934880, 2023). "If the APC gene is mutated, truncated proteins may lose their ability to bind to Bub1 and fail to properly maintain microtubule attachment to the kinetochore, leading to defects in chromosome segregation, which then leads to poor prognosis in Colon cancer patients." (PMID 37916187, 2023). "In tumor tissues of individuals with colon cancer, APC genes are frequently subjected to high levels of methylation." (PMID 37916187, 2023). "Further study using in vivo mice model e.g. cross breeding Cre-Bv8 mice (conditional Bv8 deletion) with APC Min/+ mice (colon cancer) to have Cre-Bv8-APC min/+ mice, would be worth approaching." (PMID 37090721, 2023). "The prognostic utility of RAI14 in APC-mutant colon cancer will provide early warning and increase the chance of successful treatment." (PMID 36934880, 2023). "Based on the proteome and phosphoproteome data, we classified APC-mutant colon cancer patients and revealed genomic, proteomic, and phosphoproteomic heterogeneity in APC-mutant tumors." (PMID 36934880, 2023). "PCSK9 blocking agents, especially when combined with statins, inhibit the neoplastic growth of APC/KRAS mutant colon cancer xenograft models by suppressing the KRAS/MEK/ERK pathway." (PMID 36900189, 2023). "Collectively, this work describes the phenotypic heterogeneity of APC-mutant tumors and identifies RAI14 as an important prognostic determinant for APC-mutant colon cancer patients." (PMID 36934880, 2023). "The APC gene is a key TSG; abnormal hypermethylation and mutations in the gene have been affecting most colon cancers and also some other cancers." (PMID 37901797, 2023). "In another study in colorectal cancel model, authors founded that PCSK9 induces oncogenesis in APC/KRAS mutant models of colon cancer and that systemic PCSK9 levels correlate with reduced survival in this patient cohort." (PMID 36900189, 2023). "The importance of β-catenin (independent of APC) in colon carcinogenesis gained traction after the discovery of mutations in the regulatory sequences of the β-catenin gene in APC wild-type colon cancers." (PMID 37655825, 2023). "It seems that APC-wt/MSS colon cancer is more likely to be TMIT1, which is more expected to benefit from immunotherapy." (PMID 35937946, 2022). "More than 90% of precancerous lesions in the colon involve either mutations to the APC or BRAF genes; drugs capable of specifically killing cells with these mutations should be useful for reducing the incidence of colon cancer." (PMID 36860494, 2022).